RN7SKP21 (RN7SK pseudogene 21)
Gene: Miscellaneous RNA gene on chromosome 14 (36,231,555 to 36,231,774, reverse strand). Ensembl gene ENSG00000252312.
Homologues: Orthologues: guinea pig 7SK (54% identical), mouse Gm54357 (51% identical). Paralogues in human: RN7SKP52 (91% identical), RN7SKP211 (68% identical), RN7SKP153 (66% identical), RN7SKP240 (66% identical), RN7SKP37 (66% identical), RN7SKP112 (66% identical), RN7SKP180 (66% identical), RN7SKP243 (66% identical), RN7SKP6 (66% identical), 7SK (65% identical), RN7SKP255 (65% identical), RN7SKP9 (65% identical), and 284 more.